RNU7-172P (RNA, U7 small nuclear 172 pseudogene)
Gene: Small nuclear RNA gene on chromosome 2 (54,166,944 to 54,167,007, reverse strand). Ensembl gene ENSG00000252934.
Homologues: Orthologues: chimpanzee U7 (100% identical), macaque U7 (95% identical). Paralogues in human: RNU7-34P (83% identical), RNU7-140P (81% identical), RNU7-48P (81% identical), RNU7-55P (81% identical), RNU7-88P (81% identical), U7 (81% identical), RNU7-10P (80% identical), RNU7-138P (80% identical), RNU7-167P (80% identical), RNU7-183P (80% identical), RNU7-2P (80% identical), RNU7-59P (80% identical), and 143 more.